STRA6 (signaling receptor and transporter of retinol STRA6)
Diseases named in the same sentence as STRA6 in open-access papers (continued):
Sharing a sentence is not in itself a finding about the gene and the disease.
ischemic heart disease (1 paper, 2025). "The underlying mechanisms by which Stra6 deletion and additional VitAD mediate Wnt signaling post-MI and in ischemic heart disease require further investigation." (PMID 41035698, 2025). "The impact of Stra6 on the heart and ischemic heart disease is incompletely understood." (PMID 41035698, 2025). "However, the impact of Stra6 expression on ischemic heart disease and its correlation with vitamin A availability remains to be determined." (PMID 41035698, 2025).
myocardial infarction (1 paper, 2025). Gross necrosis of the myocardium, as a result of interruption of the blood supply to the area, as in coronary thrombosis. "To address this important question, we generated a murine model with combined Stra6 deletion and VitAD that was subjected to surgically induced myocardial infarction (MI)." (PMID 41035698, 2025).
neuroblastoma (1 paper, 2021). Neuroblastoma (NB) is the most common solid, extracranial childhood tumor. "In the study of neuroblastomas, an embryonic tumor originating from the neural crest, maternal polymorphisms rather than patients (offspring) were associated with the risk of tumors; rs12442054-proximal to STRA6 was associated with the decreased risk of neuroblastomas." (PMID 34579037, 2021).
retinal disease (1 paper, 2010). "known retinal disease genes (BEST1 [NM_004183], C1QTNF5 [NM_015645], CDH3 [NM_001793], LRAT [NM_004744], RDH5 [NM_002905], RDH11 [NM_016026], RGR [NM_002921], RLBP1 [NM_000326] and STRA6 [NM_022369])." (PMID 20479888, 2010).
thyroid (1 paper, 2023). "Our study demonstrates STRA6 may serve as a prognostic marker for BRAF-mutated PTC, which may drive thyroid carcinogenesis via activation of oncogenic pathway and regulation of tumor immunosuppressive microenvironment." (PMID 36843593, 2023).
viral infection (1 paper, 2024). "The expression of RA-regulated genes, such as RARA, RARB, CRABP1, HOXB1, and STRA6, were all downregulated after HSV-1 infection, thus further demonstrating that RA synthesis was inhibited by viral infection." (PMID 38989466, 2024).
Visual impairment (1 paper, 2024). "However, investigations in Stra6 knockout mice unveiled that the generation of these visual cycle byproducts correlated with a light-induced loss of ocular retinoids and visual impairment." (PMID 38395306, 2024).
tumor (19 papers, 2014 to 2025). "Our results suggested that the four mRNA vaccine targets, namely, ADAMTS18, COL10A1, PPEF1, and STRA6, were positively correlated with the infiltration of dendritic cell, thereby activating cytotoxic T cells against tumor cells." (PMID 35874675, 2022). "Studies have also demonstrated that RBP4 activates STRA6, which drives and mediates tumor initiation, tumor growth, and the expression of stemness markers in the genesis of colon cancer." (PMID 33834191, 2021). "Further research regarding the STRA6 expression in tumor tissue and its relation with RARs expression and clinical outcome in advanced NSCLC patients is in process." (PMID 33324556, 2020). "A high STRA6 expression was correlated with a large tumour size, a late T grade and a poor histological type." (PMID 31694721, 2019). "The stably transfected cells were subcutaneously injected into the flanks of nude mice to validate the effects of STRA6 on tumour growth in vivo." (PMID 31694721, 2019). "A high STRA6 expression level was correlated with a large tumour size, an advanced T grade and a poor histological type." (PMID 31694721, 2019). "The average size of tumours was significantly decreased in the STRA6 knockdown group, and an opposite result was observed in STRA6 overexpression group." (PMID 31694721, 2019). "Mice that were fed either normal chow or HFD for 15 weeks were then injected subcutaneously with SW480 cells stably expressing control (shGFP) or STRA6 shRNA, and tumor growth was monitored for 2 additional weeks while being maintained on the dietary regimen." (PMID 28689994, 2017). "We have previously shown that knockdown of STRA6 in SW480 cells decreases tumor growth in a xenograft model." (PMID 28689994, 2017). "In our recent publication, we showed that STRA6 knockdown delayed tumor initiation by 4 days and decreased tumor progression in mice fed normal chow." (PMID 28689994, 2017). "The HFD-mediated increase in tumor growth in control tumors was accompanied by at least a 2-fold increase in STRA6 levels." (PMID 28689994, 2017). "HFD increased STRA6 levels, and downregulation of STRA6 delays and impairs tumor initiation, tumor growth, and expression of stemness markers." (PMID 28689994, 2017). "Increased levels of CSC markers and tumor growth in response to high-fat feeding are abrogated upon STRA6 silencing." (PMID 28689994, 2017). "STRA6 may contribute to the progression of BRAF-mutant PTC via regulation of immunosuppressive tumor microenvironment and activation of oncogenic pathway." (PMID 36843593, 2023). "Nevertheless, the engagement of STRA6 in tumor immune microenvironment of TC remains elusive." (PMID 36843593, 2023). "Using bioinformatics to predict miRNA, Lin and colleagues found miR-873 negatively regulates STRA6 and has a tumour suppressive role in GC, which could be reversed by STRA6 overexpression." (PMID 34785649, 2021). "Altered retinol homeostasis through aberrant STRA6 function and expression could potentially lead to an excess in proliferative signals, thus driving tumour development and other pathologies." (PMID 34785649, 2021). "We propose STRA6 expression could be related to normal retinol levels in the tumor cell cytoplasm, favoring expression of retinol nuclear receptors, and playing an essential role in NSCLC patients as improving oncological outcomes." (PMID 33324556, 2020). "Strikingly, for genes in cluster ii), which are specifically up-regulated in AAS, high expression of 7 of the top 10 genes (C3, CD74, HLA-DRA, STRA6, IGFBP4, PIGR, and TNIP1) was strongly associated with better cumulative survival than tumours with low expression of these genes." (PMID 32218455, 2020). "STRA6 was confirmed as an miR-873 target, which acted as a tumour suppressor in GC." (PMID 31694721, 2019). "Moreover, rescue assay validated that miR-873 exerted its tumour suppressive role by targeting STRA6, and our study enriched the target pool for miR-873 in GC." (PMID 31694721, 2019).
tumor (continued). "The role of STRA6 on tumour metastasis was investigated in vivo." (PMID 31694721, 2019). "Reducing STRA6 levels delayed tumor initiation in addition to decreasing tumor progression." (PMID 28689994, 2017). "Moreover, the association of STRA6 and RBP4 expression with metastasis, tumor recurrence, and therapeutic resistance suggests a role for these proteins in regulating cancer-initiating cells." (PMID 28689994, 2017). "Downregulating STRA6 or RBP4 reduced the tumor-initiating cell frequency by ∼4.5-fold." (PMID 28689994, 2017). "Additionally, the authors found that STRA6 transfection induced both a pro-apoptotic and tumor suppressive affect." (PMID 25340777, 2014). "Therefore, STRA6 may limit antitumor immunity and induce immunosuppressive tumor microenvironment in TC." (PMID 36843593, 2023). "We hypothesized high levels of CARHSP1, KIAA0895, FBMIL1, and STRA6 may promote tumor progression." (PMID 34290231, 2021). "For instance, genes such as STRA6 and MALAT1 in the tumor edge regions correlate with variations in the abundance of tumor-associated macrophages, which are critical for patient survival due to their role in tumor angiogenesis." (PMID 41045512, 2025). "The correlation between STRA6 expression and immune infiltration was analyzed by tumor immune estimation resource (TIMER) and tumor-immune system interaction database (TISIDB)." (PMID 36843593, 2023). "The result showed that the STRA6 expression was higher in the GC cell lines and tissues than in GES-1 and the adjacent non-tumour tissues." (PMID 31694721, 2019). "Knockdown of STRA6 significantly decreased tumor progression on an HFD and final tumor volumes were decreased on both regular rodent chow diet (RD) and HFD." (PMID 28689994, 2017). "The effect of RBP4 presented above, together with the previously shown effect of STRA6 on tumor progression, establish a role for the RBP4-STRA6 pathway in tumor initiation and suggest a potential role in the maintenance of colon CSCs." (PMID 28689994, 2017). "We hypothesize that the high EFFscore subgroup may secrete ANGPTL4 and MDK to activate myCAF populations, particularly LRRC15+ Fib and STRA6+ Fib, thereby driving late-stage ECM remodeling and promoting tumor invasion and metastasis." (PMID 41383622, 2025). "Importantly, some the genes upregulated upon ZNF714 knockdown (PCDH20, STRA6, ARNT2, TIMP3) were previously shown to function as tumor suppressors." (PMID 37958512, 2023). "Given the involvement of many of these genes (such as C3, CD74, HLA-DR, STRA6, IGFBP4 and PIGR) in immune-mediated processes, it is tempting to speculate that their up-regulation indicates immune-mediated tumour control that is lost in malignant tumours." (PMID 32218455, 2020). "Here, we examine the effect of HFD on tumor growth in the presence and absence of STRA6." (PMID 28689994, 2017). "In contrast, it seems that the TT genotype SNP rs351224 might not influence STRA6 localization or function, but could induce an overactivation, facilitating the retinol entry to the tumor cell, high expression of nuclear receptors, and favorable PFS and OS outcomes." (PMID 33324556, 2020).
cancer (18 papers, 2013 to 2025). A tumor composed of atypical neoplastic, often pleomorphic cells that invade other tissues. "Moreover, STRA6 promoted epithelial-mesenchymal transition via increased cancer-associated fibroblasts infiltration." (PMID 36843593, 2023). "Whilst various components of the retinoid pathway have been implicated in cancer, there is increasing evidence that STRA6 itself may have a role in tumorigenesis." (PMID 34785649, 2021). "Since STRA6 is highly overexpressed in cancer cells, fenretinide’s interaction with STRA6 in cancer cells may cause retinoid overloading and contribute to fenretinide’s anti-cancer activity." (PMID 26343735, 2015). "Another upregulated and demethylated gene in H2073 cells, STRA6, was reported as an oncogene, supporting the maintenance of cancer stem cell characteristics." (PMID 37958512, 2023). "For some cancer cells, the uptake of all-trans-retinol is perturbed by increased expression of Stra6." (PMID 36768694, 2023). "To unveil the expression pattern of STRA6 across different cancers, we analyzed the mRNA expression level of STRA6 in the TCGA cohort." (PMID 36843593, 2023). "Can we modulate cell fate decisions by chemically activating or inhibiting STRA6, and thus propose novel therapies for diseases such as cancer?" (PMID 34785649, 2021). "Retinol-binding protein (RBP), which mediates retinol transport in blood plasma, and STRA6, which is an RA receptor and translocator across the plasma membrane, are proposed as potent protooncogenes and key players in cancer stem cell maintenance." (PMID 32605249, 2020). "Retinol binding through the STRA6 upregulation activates a signalling cascade that is found to play a role in cancer initiation, maintenance and growth." (PMID 33245713, 2020). "The STRA6 expression and its signaling has been proposed drive oncogenic transformation of cancer cells." (PMID 29642915, 2018). "Because fenretinide strongly suppresses STRA6-catalyzed retinol loading and stimulates STRA6-catalyzed retinol release, fenretinide’s interaction with excessive STRA6 on cancer cells may cause retinoid overloading and contribute to fenretinide’s anti-cancer activity." (PMID 26343735, 2015). "A related recent finding is that knocking down STRA6 expression decreases the effect of fenretinide on cancer cells." (PMID 26343735, 2015). "One study shows that in mouse colon, HFD-mediated increased STRA6 may promote tumorigenesis via cancer stem cell populations." (PMID 35323693, 2022). "This idea of controlling STRA6 expression by miRNAs opens up possible therapeutic intervention, given that miRNA dysregulation has been found in a number of cancers and could contribute to sustained proliferative signals." (PMID 34785649, 2021). "Stratification of patients depending on their STRA6 expression and sensitivity to RA could help identify those cancers in which RA could be successfully used as adjuvants of chemo/radiotherapy." (PMID 34785649, 2021). "For instance, the fact that STRA6 tightly regulates vitamin A homeostasis whilst integrating signalling pathways to affect cell fate decisions may be particularly important in cancer therapy, where STRA6 may be a target to enhance retinoid combination therapy." (PMID 34785649, 2021). "We also show that vitamin A decreased urothelial atypia and therefore can speculate that vitamin A exerts its protective effects by neutralizing Stra6 and Rbp4 expression, leading to diminished cancer stem cell preservation." (PMID 32605249, 2020). "STRA6, as a transmembrane protein of RA, is overexpressed in many cancer types." (PMID 31694721, 2019). "STRA6 was first known as a cancer cell surface marker before it was known as the RBP receptor." (PMID 26343735, 2015).
cancer (continued). "Fenretinide’s dependence on STRA6 in cancer treatment was demonstrated in a recent study." (PMID 26343735, 2015). "Since certain cancer cells are known to have more than 100 fold higher STRA6 expression levels, this strategy may also be used to target cancer cells." (PMID 26343735, 2015). "The retinoids with the promising role in chemoprevention of premalignant lesions in the head and neck have been the focus of cancer intervention treatment which Stra6 unregulated RA-responsive genes unregulated by DNA damage with important role in cell death responses." (PMID 24564241, 2013). "Thus, the exact role of STRA6 in cancer and stem cells remains to be fully elucidated." (PMID 37958512, 2023). "RBP4 activates STRA6, leading to activation of Janus kinase and STAT3/STAT5, which results in pro-inflammatory response and tumorogenesis.This results in cancer progression, migrations, and metastasis." (PMID 41007818, 2025). "The oncogenic activity of Stra6 was mediated by STAT3, which is a known driver of cancer." (PMID 36768694, 2023).
metabolic disease (2 papers, 2020 to 2026). A congenital disorder (due to inherited enzyme abnormality) or acquired (due to failure of a metabolically important organ) disorder resulting from an abnormal metabolic process. "CRBP1 is part of the STRA6 complex on the intracellular side and assists with transport of retinol into the cell and sites of its use, and is also linked to metabolic disorders." (PMID 31884477, 2020). "Changes in RBP4, STRA6 and CRBP1, associated with vitamin A’s role in metabolic disease may be linked with the metabolic abnormalities that occur in AD." (PMID 31884477, 2020).
cardiovascular disease (1 paper, 2025). "STRA6 is the RBP4 membrane receptor and circulating RBP4 levels are associated with cardiovascular disease." (PMID 41035698, 2025).
infection (1 paper, 2026). The state of being infected such as from the introduction of a foreign agent such as serum, vaccine, antigenic substance or organism. "At the site of infection, expression of genes regulating vitamin A transport and metabolism (STRA6, RXRα, RBP4) increased (P ≤ 0.002) in non-lesion lung relative to diseased lung." (PMID 41476140, 2026).
kidney disease (1 paper, 2016). "Although RA and RARα agonist have been demonstrated to provide protection in several experimental models of kidney disease, there are very few studies to report the change of STRA6/CRBP1 cascades in kidney diseases." (PMID 27256691, 2016). "Accordingly, it is reasonable to hypothesize that STRA6 and its cascades could be altered and involved in pathogenesis of kidney diseases." (PMID 27256691, 2016).
STRA6 also shares sentences with these, for which no sentence is quoted: alveolar capillary dysplasia (2 papers); cardiovascular malformations (2); adenoma (1); atherosclerosis (1); bladder cancer (1); clear cell renal cell carcinoma (1); colobomatous microphthalmia (1); colon (1); colon adenocarcinoma (1); Cornelia de Lange syndrome 4 (1); COVID-19 (1); diabetic retinopathy (1); endometritis (1); gallbladder cancer (1); glioblastoma (1); hepatocellular carcinoma (1); Hypertension (1); Infertility (1); liver cirrhosis (1); Marfan syndrome (1); memory impairment (1); microdeletion syndrome (1); Nephroblastoma (1); neurodevelopmental disorder (1); Opitz G/BBB syndrome (1); optic nerve hypoplasia (1); osteogenesis imperfecta (1); pancreatic cancer (1); papillary thyroid carcinoma (1); ptosis (1).
A further 5 diseases each share a sentence with STRA6 in 1 paper.